NAT2 (N-acetyltransferase 2)
Description:
Catalyzes the N- or O-acetylation of various arylamine and heterocyclic amine substrates. Participates in the detoxification of a plethora of hydrazine and arylamine drugs, and is able to bioactivate several known carcinogens.
Synonyms: NAT-2; PNAT; AAC2
Tractability: Small molecule: a structure with a bound ligand is known; it has a high-quality binding pocket.
Target class: Enzyme; Transferase
Safety:
Unwanted effects reported when the protein is acted on. In parentheses: how it was acted on, where the effect was seen, and who reports it.
adverse events (source: ClinPGx)
anti-TB hepatitis (source: ClinPGx)
aspirin intolerance (source: ClinPGx)
clearance of isoniazid (source: ClinPGx)
drug toxicity (source: ClinPGx)
grade 2-4 anemia (source: ClinPGx)
hepatotoxicity (source: ClinPGx)
liver injury (source: ClinPGx)
phenytoin toxicity (source: ClinPGx)
phenytoin toxicity resulting from isoniazid-phenytoin interaction (source: ClinPGx)
toxic liver disease (source: ClinPGx)
transcription of the NAT2 gene (source: ClinPGx)
Gene: Protein-coding gene on chromosome 8 (18,391,252 to 18,401,218, forward strand). Ensembl gene ENSG00000156006.
Subcellular location: Cytoplasm
Pathways (Reactome):
Drug ADME: Paracetamol ADME
Metabolism: Acetylation
Gene Ontology:
Molecular function: arylamine N-acetyltransferase activity; N-hydroxyarylamine O-acetyltransferase activity; protein binding; protein-cysteine S-acyltransferase activity; acetyltransferase activity
Biological process: xenobiotic metabolic process
Cellular component: cytosol; cytoplasm
Genetic constraint (gnomAD): Loss-of-function variants: 1 observed, 0.3 expected, observed/expected ratio (o/e) 3.39. That is too few expected variants to judge how well the gene tolerates losing a copy. Missense variants: 427 observed, 351.08 expected, observed/expected ratio (o/e) 1.22, 90% interval 1.12 to 1.32. Synonymous variants: 137 observed, 131.66 expected, observed/expected ratio (o/e) 1.04, 90% interval 0.9 to 1.2.
Homologues: Orthologues: chimpanzee NAT2 (97% identical), macaque NAT2 (89% identical), guinea pig Nat1 (76% identical), mouse Nat2 (75% identical), rat Nat2 (74% identical), rat Nat3 (73% identical), mouse Nat1 (72% identical), rat Nat3 (67% identical), mouse Nat3 (66% identical), zebrafish si:dkey-78a14.4 (40% identical), zebrafish zgc:101040 (39% identical). Paralogues in human: NAT1 (81% identical).
Diseases named in the same sentence as NAT2 in open-access papers:
NAT2 is named in the same sentence as 130 diseases in open-access papers, as found by Europe PMC text mining. Sharing a sentence is not in itself a finding about the gene and the disease. The quoted sentences say what the papers report.
tuberculosis (67 papers, 2008 to 2026). A chronic, recurrent infection caused by the bacterium Mycobacterium tuberculosis. "While the impact of the highly polymorphic NAT2 locus on the pharmacokinetics of INH has long been recognized, there are relatively few data on the distribution of NAT2 alleles in patients with tuberculosis in Latin America." (PMID 40239986, 2025). "The risk was found to be 4.62 times greater in tuberculosis patients with NAT2 hypermethylation than those with NAT2 hypomethylation (OR 4.62; 95% CI 1.12, 19.05; P = 0.034)." (PMID 40133601, 2025). "This emphasizes the potential use of NAT2 demethylation index as a diagnostic biomarker for ATDILI in tuberculosis patients." (PMID 40133601, 2025). "It included 37 studies with 1527 cases and 7184 controls, and found that the slow NAT2 acetylator phenotype was associated with an increased risk of DILI during anti-tuberculosis treatment." (PMID 38927494, 2024). "This study aimed to identify prevalent NAT2 single nucleotide polymorphisms (SNPs) and infer their potential effects on enzyme function among Kenyan volunteers with tuberculosis (TB) infection." (PMID 38184575, 2024). "Prior to the present work, multiple studies have highlighted the importance of different NAT2 polymorphisms, especially the slow acetylator phenotype, in susceptibility to drug-induced hepatotoxicity, particularly in the context of anti-tuberculosis treatment." (PMID 38927494, 2024). "The second analysis included 14 studies with 474 cases and 1446 controls, and also confirmed a significant association between NAT2 slow acetylators and the risk of anti-tuberculosis drug-induced liver injury." (PMID 38927494, 2024). "The human N-acetyltransferase 2 enzyme, encoded by the NAT2 gene, plays an important role in the metabolism of isoniazid, the main drug used to treat tuberculosis." (PMID 39065614, 2024). "A recent pharmacokinetic cohort study found that isoniazid concentration and NAT2 genotype can predict the risk of systemic drug reactions during tuberculosis treatment." (PMID 35509409, 2022). "Distinct N-acetyltransferase 2 (NAT2) slow acetylators genotypes have been associated with a higher risk to develop anti-tuberculosis drug-induced hepatotoxicity (DIH)." (PMID 35588539, 2022). "The variable response to Brazilian treatment for tuberculosis standard dosing of isoniazid, its relationship with genetic variants of NAT2, and demographic/clinical features were described in the present study." (PMID 35588539, 2022). "The purpose of this study is to establish a PPK model for INH and its major metabolite AcINH in tuberculosis patients and healthy Chinese participants,and assess the influence of NAT2 polymorphism on the PK/PD of INH." (PMID 35928262, 2022). "Studies have shown that carriers of NAT2 slow acetylation genotype are generally more susceptible to hepatotoxicity induced by isoniazid anti-tuberculosis drug regimens." (PMID 34552491, 2021). "Fifty-one percent of Thais were carriers of T allele in rs1041983 (NAT2 c.282C>T), which is associated with increased risk of liver toxicity upon treatment of anti-tuberculosis drugs." (PMID 33144648, 2020). "It has been shown that polymorphic variants of the GSTT1, GSTM1, and NAT2 genes can potentially modulate the risk of tuberculosis development in ethnic Russians." (PMID 33092525, 2020). "NAT2 acetylator status was significantly associated with the likelihood of experiencing anti-tuberculosis drug-related hepatotoxicity." (PMID 30871660, 2019). "Our review and meta-analysis updates and adds to the evidence base on associations between NAT2 and anti-tuberculosis drug-related toxicity." (PMID 30871660, 2019). "There is substantial evidence for the association between NAT2 variants and anti-tuberculosis drug-related toxicity outcomes, as previously identified and as our systematic review confirmed." (PMID 30871660, 2019).
tuberculosis (continued). "Forty-six articles reported data for the association between NAT2 variants and anti-tuberculosis drug-related toxicity; from these articles, 40 distinct patient cohorts were identified." (PMID 30871660, 2019). "Fundamentally, Africa and the Indian sub-continent are two of the most infested regions with tuberculosis; preemptive screening of NAT2 alleles would be greatly helpful to prevent ADR events." (PMID 30356105, 2018). "Variants in NAT2 gene affect the activity of anti-tuberculosis drugs and result in three different phenotypes: rapid (RA), intermediate (IA) and slow acetylators (SA)." (PMID 25544508, 2014). "This is in line with our finding that slow acetylators with NAT2*5/6 has a significantly higher risk of anti-tuberculosis drug-induced hepatitis than other genotypes." (PMID 24465778, 2014). "The NAT1 and NAT2 genes encode enzymes responsible for the acetylation of various nitrogenous compounds, including the antimycobacterial drug isoniazid, which is the primary treatment for tuberculosis." (PMID 40171627, 2025). "Similarly, the absence of comprehensive data on co-morbidities associated with ATDILI complicates the interpretation of our finding that NAT2 hypermethylation was independently associated with a higher incidence of ATDILI in tuberculosis patients." (PMID 40133601, 2025). "Genetic variation at NAT2 has been long recognized as the cause of differential ability to metabolize a wide variety of drugs of therapeutic use in diseases with high prevalence such as tuberculosis, arrhythmia and hypertension." (PMID 18773084, 2008). "Mutant NAT2 alleles associated with slower acetylation were common in our cohort resulting in a predicted proportion of fast acetylators of 19.2%, similar to recent reports in adult patients with tuberculosis from Peru, Bolivia and Argentina, and in children with tuberculosis in Venezuela." (PMID 40239986, 2025). "N-acetyltransferase 2 (NAT2) genetic polymorphisms were related to anti-tuberculosis (TB) -drug-induced liver injury in Chinese patients with TB." (PMID 37719844, 2023). "We aimed to summarize population pharmacokinetic studies of isoniazid in tuberculosis (TB) patients with a specific focus on the influence of N-acetyltransferase 2 (NAT2) genotype/single-nucleotide polymorphism (SNP) on clearance of isoniazid." (PMID 35852584, 2022). "Another limitation is the insufficient data on oxidative stress, which hinders the establishment of a definitive link between NAT2 hypermethylation and increased oxidative stress in tuberculosis patients with ATDILI." (PMID 40133601, 2025). "N-acetyltransferase 2 (NAT2) is crucial in metabolizing several drugs, including isoniazid, used in tuberculosis (TB) treatment." (PMID 40430848, 2025). "After accounting for the factors mentioned earlier, a multivariate logistic regression analysis revealed a strong association between NAT2 hypermethylation and a significantly increased risk of ATDILI in tuberculosis patients." (PMID 40133601, 2025). "Kaplan–Meier analysis unveiled a notable association between lower NAT2 demethylation index and a higher incidence of ATDILI in tuberculosis patients, as confirmed by Cox regression analysis while accounting for confounding variables." (PMID 40133601, 2025). "Compared to healthy controls, tuberculosis patients had significantly reduced NAT2 demethylation index, indicating NAT2 hypermethylation in tuberculosis patients (P < 0.0001)." (PMID 40133601, 2025). "After accounting for confounding factors, it was found that NAT2 demethylation index in tuberculosis patients with ATDILI remained significantly lower than that in those without ATDILI (odds ratio, OR 8.88; 95% CI 1.30, 60.87; P = 0.026)." (PMID 40133601, 2025). "One limitation is the inability to investigate the NAT2 demethylation index in liver-specific cells of tuberculosis patients with ATDILI." (PMID 40133601, 2025).
tuberculosis (continued). "In addition to this, our findings of NAT2 promoter hypermethylation in patients with ATDILI support the hypothesis that epigenetic modifications of NAT2 might predispose individuals to hepatotoxicity during anti-tuberculosis therapy." (PMID 40133601, 2025). "Kaplan–Meier analysis uncovered that tuberculosis patients with lower NAT2 demethylation index had a significant higher cumulative rate of ATDILI occurrence compared to those with higher NAT2 demethylation index (log-rank: χ2 = 9.870, P = 0.002)." (PMID 40133601, 2025). "Isoniazid metabolism has been well studied in part because a polymorphism in N‐acetyltransferase 2 (NAT2 polymorphism) was detected in the 1950s when isoniazid was first used to treat tuberculosis (TB), with acetylation shown to be a key step in its metabolism." (PMID 39704445, 2025). "Compared to healthy volunteers, tuberculosis patients had significantly reduced NAT2 demethylation index." (PMID 40133601, 2025). "Previous studies have reported associations between differential DNA methylation levels in promoter regions of genes encoding metabolic enzymes—such as CYP2E1, CYP2D6, GSTP1, and NAT2—and ATDILI risk in tuberculosis patients." (PMID 40133601, 2025). "Specifically, two relevant systematic reviews and meta-analyses explored the relationship between NAT2 polymorphisms and drug-induced liver injury (DILI) in the context of tuberculosis treatment." (PMID 38927494, 2024). "The presence of NAT2 polymorphisms, considered to be slow acetylators, has been associated not only with increased risk of DILI by anti-tuberculosis drugs, but also with increased severity of liver damage." (PMID 38927494, 2024). "The first study evaluated the potential association between NAT2 polymorphisms and DILI during anti-tuberculosis treatment." (PMID 38927494, 2024). "NAT2 plays a crucial role in the metabolism and inactivation of carcinogens and drugs used in the treatment of infections and chronic diseases, including tuberculosis, leprosy, and arterial hypertension, among others." (PMID 39065614, 2024). "Detecting NAT2 phenotypes has been considered from the beginning of tuberculosis treatment in order to avoid drug-related liver injury and determine appropriate dosing." (PMID 38001469, 2023). "For 157 tuberculosis patients, seven different NAT2 genotypes including *4/*4 (n = 72), *4/*5 (n = 6), *4/*6 (n = 31), *4/*7 (n = 25), *6/*6 (n = 12) and *7/*7 (n = 4), *5/*7 (n = 2), and *6/*7 (n = 5) were observed." (PMID 35928262, 2022). "The frequency of NAT2 genotypes was analysed by DNA sequencing in 162 patients undergoing tuberculosis therapy." (PMID 35588539, 2022). "This study aimed to investigate the association between NAT2 genotypes and the risk of developing DIH in Brazilian patients undergoing tuberculosis treatment, focusing on the discrimination of homozygotes and compound heterozygotes slow acetylators." (PMID 35588539, 2022). "NAT2 is mainly involved in all aspects of the metabolism of isoniazid, which is also a hot spot in the study of drug-induced liver injury during anti tuberculosis (anti-TB) in the past 20 years." (PMID 34552491, 2021). "Further studies are also recommended to investigate and monitor the isoniazid safety and treatment outcome in patients undergoing treatment for tuberculosis with different NAT2 acetylation phenotypes." (PMID 33392048, 2020). "The objective of this systematic review and meta-analysis was to evaluate evidence on the effect of NAT2 on anti-tuberculosis drug-related toxicity in TB patients receiving anti-tuberculosis treatment." (PMID 30871660, 2019). "Isoniazid, a potent anti-tuberculosis drug, is metabolized by genetically polymorphic enzyme NAT2, and its plasma concentration is predictive of pulmonary tuberculosis outcomes." (PMID 29589062, 2018). "The NAT2 enzyme metabolizes isoniazid, an anti-tuberculosis drug co-administered with rifampicin for the six months of tuberculosis treatment." (PMID 30397233, 2018).
tuberculosis (continued). "A 49.1% NAT2 genotype-phenotype discordance rate in tuberculosis-infected Ethiopian patients is reported previously." (PMID 29589062, 2018). "We also believe that in the near future, the treatment of tuberculosis should become individualized, namely, drugs and dosages should be adapted according to the NAT2 phenotypic profile of each patient." (PMID 27332812, 2016). "Greenland has a high incidence of tuberculosis, and individual dosing of isoniazid, according to NAT2 status, has been shown to improve treatment and reduce side effects." (PMID 27829488, 2016). "The disposition of anti-tuberculosis drug is related to the activity of many drug-metabolizing enzymes (DMEs), including NAT2, CYP2E1and GST." (PMID 24465778, 2014). "Isoniazid (INH), a key drug of the currently recommended regimen for patients with tuberculosis, is metabolized by genetically polymorphic N-acetyltransferase 2 (NAT2)." (PMID 23150149, 2013). "Isoniazid (INH), a key agent in the treatment of tuberculosis (TB), is metabolized primarily by the genetically polymorphic N-acetyltransferase 2 (NAT2) enzyme." (PMID 24383060, 2013). "We propose here that the pharmacotherapy against tuberculosis with INH should be individually designed by stratification based on NAT2 genetic information in order to achieve the greatest success outcome for each patient." (PMID 23150149, 2013). "Our results clearly indicate a great potential of the NAT2 genotype-guided dosing stratification of isoniazid in chemotherapy for tuberculosis." (PMID 23150149, 2013). "In summary, our meta-analysis indicates that CYP2E1, NAT2 and GSTM1 genetic variation is significantly associated with anti-tuberculosis drug-induced liver injury." (PMID 23082213, 2012). "The relationship between genetic variants of NAT2 and CYP2E1 with the plasma concentration of isoniazid and acetylisoniazid and their possible association with hepatotoxicity was observed in Iranian patients with tuberculosis." (PMID 39858601, 2025). "Notably, NAT2 demethylation exhibited an inverse correlation with serum aminotransferase levels in tuberculosis patients within 8–60 days after initiating treatment." (PMID 40133601, 2025). "Ultimately, overcoming these challenges would enable NAT2 methylation analysis to complement existing clinical biomarkers and genetic tests, offering a valuable tool for the early detection and personalized management of ATDILI risk in tuberculosis patients." (PMID 40133601, 2025). "Despite this evidence, it currently remains unclear whether NAT2 genotyping should be recommended prior to anti‐tuberculosis treatment." (PMID 40171627, 2025). "In addition to this, our findings revealed an independent association between NAT2 demethylation index and an increased risk of ATDILI in tuberculosis patients." (PMID 40133601, 2025). "A small randomized controlled trial suggested that the NAT2 genotype‐guided regimen could reduce isoniazid‐induced liver injury and early treatment failure in the 6‐month four‐drug standard treatment of tuberculosis." (PMID 35509409, 2022). "In the present study, the slow acetylators of the NAT2 genotype did not contribute to the elevated risk of ATDIH development in tuberculosis patients." (PMID 31245212, 2019). "In conclusion, the present pharmacogenetics clinical trial with a PROBE-design demonstrated that NAT2 genotype-guided dosing stratification of INH could improve treatment outcomes in patients with drug-sensitive tuberculosis." (PMID 23150149, 2013). "In the present study, NAT2 genotype-guided dosing stratification of INH obviously improves therapeutic efficacy against INH-sensitive tuberculosis during the first 8 weeks, although the PGx-treatment could not start until a couple of days after the first dose." (PMID 23150149, 2013).